IL1B (interleukin 1 beta)
Diseases named in the same sentence as IL1B in open-access papers (continued):
Sharing a sentence is not in itself a finding about the gene and the disease.
tumor (continued). "First, fibroblasts-activating factors such as IL-1β and TNF-α are secreted by immune and/or tumor cells in the damaged tissue environment." (PMID 26501341, 2015). "Tumor masses from mice treated with STM showed a significantly increased production, per mg of masses, of both IFN-γ and IL-1β cytokines at 30 days PTI (P < 0.01), whereas the IL-1β was increased already at 10 days PTI (P < 0.01)." (PMID 26158862, 2015). "We then examined the influence of IL-1α expression on the ability of tumor cells to adhere to MVEC and MVEC previously treated with 10U/mL of human recombinant IL-1β for 24 hours." (PMID 26460957, 2015). "TANs in turn can then influence the tumor niche through therelease of cytokines (e.g., TNF-α, IL-1β, IL-12), chemokines (members of the CXC and CCsubfamilies), ROS, and growth factors." (PMID 26108096, 2015). "A number of reports have established that IL-1β induces the expression of either HIF-1α or NFκB, two of the main hypoxia sensitive pathways, which are involved in tumor progression by promoting angiogenesis, cell migration, and invasiveness." (PMID 26696754, 2015). "In particular, activation of the inflammasome in DCs leads to the production of IL-1β and subsequent recruitment of γδ T cells and priming of CD8 T cells against tumor antigens." (PMID 26486085, 2015). "Therefore, chronic presence of IL-1β within the ovarian microenvironment may enhance malignant transformation and underscores the complexity among cancer cells within their microenvironment for tumor progression." (PMID 26357657, 2015). "The levels of cytokines and chemokines, including IL-1β, IL-6, GM-CSF, G-CSF, MCP-1 and TNF-α, were much higher in tumour tissue lysates than in non-tumour tissue." (PMID 26581194, 2015). "TNF-α (and IL-1β) induced the release of CCL2, CXCL8 and CCL5 by MSCs and CAFs generated by prolonged stimulation of MSCs with Tumor CM of MDA-MB-231 and MCF-7 cells." (PMID 25928089, 2015). "The total amount of IL-1β in the spleens, instead, was comparable in both STM-treated and untreated tumor-bearing mice, at day 10 and 30 PTI, and significantly increased in comparison to free-tumor mice." (PMID 26158862, 2015). "At the same time, miR-106a can also enhance the production of IL-1β, IL-6, IL-8 and TGF- β, and thus affect the tumor microenvironment to contribute to the development of drug resistance." (PMID 25950430, 2015). "IL-1β in tumors is typically produced by PSCs, inflammatory and tumor cells, is involved in macrophage recruitment and PSC activation, and both IL-1β and CXCL1 worsen desmoplasia." (PMID 26641266, 2015). "Cytokines, such as TNF-α, IL-1α, IL-1β, IL-6, and TGF-β, are produced by tumor cells and tumor-infiltrating lymphocytes and can greatly influence cellular radiosensitivity and the onset of tissue complications." (PMID 26569225, 2015). "High levels of pro-inflammatory factors, such as GM-CSF, IL-1β, IL-6, and S-100 within the TUMIC induce recruitment and expansion of MDSCs, and enhance their pro-tumor activity." (PMID 25072019, 2014). "Overall, the results of this study showed that the administration of asiaticoside significantly reduced the percent of tumour growth that is significantly correlated with MIBI uptake ratios, and this is also correlated with caspase-3, TNF-α and IL-1β values." (PMID 24667059, 2014). "By synergizing with HMGB1, released from dying tumor cells and signaling through toll-like receptor (TLR) 4, activated DC are licensed to prime an anti-tumor immune response in a caspase-1- and IL-1β-dependent manner." (PMID 24795727, 2014). "Generally, the increases of iNOS activities related to the proinflammatory agents - endotoxin, IL-1β, TNF-α and interferon-γ can be induced shock and over inflammatory responses in the body, and over expressions of iNOS also induced tumor neovascularization." (PMID 25477992, 2014).
tumor (continued). "Antibodies against the IL-1β and TNF-α receptors were added to media that had been conditioned by the macrophage-tumor cell co-cultures and inhibition of VEGF-C was observed in macrophages co-cultivated with the tumor cells." (PMID 25120672, 2014). "Such epithelial permeability results in the stimulation of macrophages and granulocytes in mucosal tissue followed by cytokine production such as IL-1β, IL-6 and MIP-2 that are required for epithelial proliferation and tumor development." (PMID 24520376, 2014). "Altogether, the increased expression of IL-1β and IL-6 together with proangiogenic effects of TP-expressing NSCLC on endothelium can contribute to tumor growth, implying TP as a target for antiangiogenesis in NSCLC." (PMID 24819505, 2014). "Tumor-secreted IL-6 has been reported to restores MDSC accumulation and is a downstream mediator of the IL-1β–induced expansion of MDSC." (PMID 25238263, 2014). "An activatory cross-talk is then established at the tumor site between MDSC and γδ17, by which IL-17 induces IL-1β and IL-23 production by MDSC and these cytokines promote further differentiation and activation of γδ17 T cells." (PMID 25505472, 2014). "Proinflammatory cytokines, i.e., IL-1β, TNF-α, IL-6 produced by tumor or host tissue due to tumor presence leads to both systemic and local inflammation in cancer." (PMID 25415607, 2014). "We then measured the expression of IL-1 proteins (IL-1α and IL-1β), CXCL8/IL-8, and VEGF family proteins (VEGF-A, -C, and -D) in cancer cells and/or tumor stromal macrophages in lower and highly metastatic tumors." (PMID 24924428, 2014). "Here, we provided specific evidence for accumulation of marrow fat cell-supplied lipids by tumor cells, and demonstrated that the accelerated growth and invasiveness involves upregulation of tumor-derived FABP4, IL-1β and HMOX-1." (PMID 24240026, 2013). "However, several studies have suggested that IL-1β may have a role instead in promoting tumorigenesis, since reducing or eliminating IL-1β can prevent tumor metastases and progression, thus suggesting that inflammasome signaling may play a more complex role in the tumor-immune system interaction." (PMID 24409181, 2013). "The levels of β-END, CRF, and IL-1β were analyzed by ELISA; immunohistochemistry was performed to detect the expressions of β-END, POMC, and μ-OR in the tumor and adjacent tissue." (PMID 24187573, 2013). "In agreement, ω-3 PUFAs were found to inhibit in vitro the expression of IL-1β and IL-6 cytokines in AR42J pancreas acinar tumor cells stimulated by the pancreatitis-inducer cerulean." (PMID 23691510, 2013). "In contrast to IL8 and IL1β which promote tumor growth, CCL3 possesses antitumor effects in preclinical models and has been investigated as a tumor immunotherapy strategy." (PMID 23762239, 2013). "IL-1β promoted IL-17 production from CD4+ T cells, which in turn attenuated the anti-tumor effect of chemotherapy via an IL-17-dependent proangiogenic effect." (PMID 24409181, 2013). "Both TNF-α and IL-1β, also found to be upregulated following PTT, can promote tumor growth by inducing IL-6 expression." (PMID 23935927, 2013). "We reveal that exposure to lipids supplied by marrow adipocytes induces expression of lipid chaperone FABP4, pro-inflammatory interleukin IL-1β, and oxidative stress protein HMOX-1 in metastatic tumor cells and stimulates their growth and invasiveness." (PMID 24240026, 2013). "Analysis of tumor-infiltrating CD45+ leukocytes showed consistent Lov-mediated upregulation of IFNγ and IL-1β (M1 markers) and downmodulation of IL-10, CD206 and CCL22 (M2 markers)." (PMID 24317954, 2013). "Increased serum levels of proinflammatory cytokines such as IL-1β, IL-6, and TNF-α were found in tumor angiogenesis induced animals." (PMID 23300633, 2012). "ATP released from dying tumor cells acts on P2X7 purinergic receptors of dendritic cells, which can lead to inflammasome activation and further IL-1β secretion." (PMID 22768222, 2012).
tumor (continued). "To investigate the effects of pardaxin on MN-11 cell functions, we detected TNF-α, IL-1β, and MIP-1α concentrations in serum after treatment of tumor-bearing mice with pardaxin." (PMID 23015777, 2012). "We then detected cytokines IL-1β, IL-6, IL-17A, IL-21, IL-23 or TGF-β by ELISA in sera and supernatants from both normal and tumor tissues cultured ex vivo." (PMID 22994684, 2012). "HK1-derived IL-1β secretion significantly abolished tumour growth in nude mice in vivo starting at day 15, although tumour growth between HK1-vector and HK1-IL-1β cells was similar during the first week." (PMID 23065753, 2012). "Our findings show that the expression of inflammasomes and the proinflammatory cytokine, IL-1β, in tumour cells is significantly correlated with better survival in NPC patients, suggesting a role of tumour inflammasomes in tumour suppression." (PMID 23065753, 2012). "So IL-1β is upstream of VEGF in the angiogenic pathway and therefore plays a key role in the expansion of the vascular compartment during tumor progression." (PMID 22296757, 2012). "Paradoxically, many of the proinflammatory cytokines induced after chemotherapy, particularly IL1β, IL6, and IFNα/β, can exert both tumor-inhibiting and tumor-promoting effects (double-edged sword)." (PMID 22400040, 2012). "ASMq treated animals had reduced tumour volume compared to model and increased concentrations of TNF-α, IL-1β and IL-2 compared to untreated and to cyclophosphamide-treated animals." (PMID 22978453, 2012). "We found that the infiltration of leukocytes, myeloid cells and neutrophils was dramatically higher in B16F10-IL-1β tumours, compared with B16F10-pro-IL-1β and B16F10-vector tumours." (PMID 23065753, 2012). "In PGCG, the TNF-α, IL-6 and IL-1β interrelations may control the cellular activities of the different cell populations (multinuclear cells, monocytes/macrophages, spindle fibroblasts/osteoblasts) contributing possibly mainly in the mechanisms of tumor growth, and occasionally of osteolysis." (PMID 22157665, 2012). "The inhibitory activity of IL13, IL1b, PTGS2, NOS2, and CTLA4 on the immune response would enhance tumor growth." (PMID 22013484, 2011). "When DC vaccine was pulsed with tumor antigens along with CT extract, the levels of TNF-α and IL-1β were dramatically increased with a dose-dependent response and more immunologic and co-stimulatory molecules were expressed on the DC surface." (PMID 19001481, 2011). "The incidence of TNFα & IL-1β was further increased in IDC patients in whom disease has relapsed, suggesting that these two cytokines push forward processes of tumor progression and recurrence." (PMID 21486440, 2011). "One study of oesophagogastric cancers showed cytokine protein concentrations of IL-1β, IL-6 and TNF-α are significantly elevated in tumour tissue." (PMID 21760776, 2011). "Our findings support this possibility because they indicate that TNFα, and to a lower extent also IL-1β, induce EMT properties in the tumor cells." (PMID 21486440, 2011). "By day 7, IFNγ, CSF2, CXCL10, GZMB, PTGS2, TNFα, CD80, CCL22, IL12a, IL13, IL1b, IL6, NOS2, and CTLA4 were significantly upregulated in the tumor-bearing mice bladders and AGTR2 and GATA3 were downregulated." (PMID 22013484, 2011). "Neutralizing antibodies to cytokines GM-CSF, IL-1β, IL-6, VEGF, or TNFα were tested in PBMC-tumor cell line co-cultures to determine which factor(s) was most important for induction." (PMID 21658270, 2011). "There is evidence that major inflammatory cytokines (such as IL-1β, IL-6, IL-23 and TNF-α promote tumor development by acting directly or indirectly on neoplastic cells." (PMID 20525350, 2010). "The connection including TGM2, IL1B, and PLAU and the connection including RAB25, SNAI1, and CDH1 were suggested to be related to tumor invasion by IPA." (PMID 20142997, 2010).
tumor (continued). "There is evidence that some inflammatory cytokines (such as IL-1β, IL-6, IL-23 and TNF-α promote tumor development by acting directly or indirectly on neoplastic cells." (PMID 20525350, 2010). "These factors, including TNF-α, IL-1α, IL-1β, VEGF, and fibroblast growth factor 2 (FGF-2), raise leptin levels and promote tumor growth and differentiation." (PMID 19017403, 2008). "In contrast, mRNA for IL-1β, IL-6, IL-8, and TNF-α were detected in tumour tissue at significantly elevated concentrations: IL-1β P<0.001; IL-6 P<0.001; IL-8 P<0.001; TNF-α P=0.006." (PMID 17088911, 2006). "Interleukin-6 is the main inducer of the APPR in human hepatocytes and both IL-1β and TNF-α are capable of inducing IL-6 production from both tumour and host cells." (PMID 17088911, 2006). "Monocytes are known to be important mediators of anti-tumour ADCC and are also known to secrete the cytokines tumour necrosis factor alpha (TNF-alpha) and interleukin 1 beta (IL-1 beta), both of which have been shown to bring about tumour cell lysis." (PMID 7669568, 1995). "The anti-tumor effect of IL-37 results from the suppression of tumor-promoting cytokines, such as IL-1β, which activates IL-6 and TNF, direct effects on tumor cells, and reduction of cell proliferation by interfering with NF-κB, MAPK, and signal transducer and activator of transcription 3 (STAT3)." (PMID 41596472, 2026). "Furthermore, QUE downregulated the expression of key inflammatory factors (IL1β, CXCL8, and MMP9), inhibiting neutrophil activation and infiltration, as well as suppressing tumor growth in CRC." (PMID 41601690, 2026). "Indeed, pharmacological disruption of this axis using AMD3100, a CXCR4 antagonist, significantly reduced both IL-1β and CXCL12 secretion, prevented adipocyte reprogramming, and suppressed tumor cell proliferation." (PMID 42316277, 2026). "Notably, IL-1β, NOS2, COX-2, IL-10, and VEGF were consistently upregulated in tumor tissues of ETBC mice." (PMID 41939865, 2026). "Tumor-derived factors such as granulocyte colony-stimulating factor (G-CSF), granulocyte-macrophage colony-stimulating factor (GM-CSF), monocyte chemoattractant protein-1 (MCP-1), and interleukin-1 beta (IL-1β) enhance MDSC recruitment." (PMID 40918452, 2025). "IHC staining disclosed a significantly suppressed expression of senescence marker P21 and SASP cytokines like IL6 and IL1β in tumor samples, regardless of GDC-0879 mono- or combined therapy with anti-PD1." (PMID 40781221, 2025). "In our study, we also showed that IL-1β stimulation induced the release of PD-L1-enriched TEVs, with consequent implications through paracrine mechanisms on TME response and immune surveillance mechanisms against circulating tumor cells." (PMID 40725070, 2025). "In our CAM tumor model, we showed that IL-1β expression levels in tumor lysates of VNP20009 and PBS controls were similar, suggesting that the reduced presence of VNP20009 on tumors was insufficient to elicit the anti-tumor immune response in the CAM model." (PMID 39873483, 2025). "Moreover, in chemotherapy-resistant breast cancer, IL-1β + CXCL3 + CD4 + T cells mediate neutrophil ferroptosis, suppressing anti-tumor immunity." (PMID 41326356, 2025). "Although no tumor cells were detected in the hypothalamus, unbiased profiling under testosterone-neutralizing conditions revealed increased signaling of interleukin-1 beta (IL-1β) and tumor necrosis factor (TNF)." (PMID 41221269, 2025). "Some studies suggested that inhibiting IL1B activity could decrease activity of MAPK and NF-κB pathways, thereby reducing inflammatory responses and tumor cell proliferation." (PMID 40535567, 2025). "This analysis suggested that p38 could activate the downstream tumor-promoting inflammatory factors, such as TNF, IL1B, and NFkB, which are predicted to be the top-activated factors in the GBM PNZ." (PMID 39805854, 2025).
tumor (continued). "Nevertheless, while CCL5 became a more dominant ligand for CCR5 in the KPC-4545 tumor, CCL4 remained a dominant ligand for CCR5 and CXCL12, CXCL10, and CXCL16 arose as major ligands for different receptors in the KPC-3403 model following anti-IL-1β treatment." (PMID 39948655, 2025). "In cancer patients, the tumor microenvironment triggers a persistent systemic inflammatory response characterized by elevated cytokines such as IL-6, TNF-α, and IL-1β, which can impair renal vascular tone and lead to renal hypoperfusion and structural kidney damage over time." (PMID 40722492, 2025). "Furthermore, coculture of macrophages with tumor cells increased LCN2 protein levels, an effect that was abolished by the IL-1R antagonist anakinra, indicating that IL-1β–IL-1R signaling mediates macrophage-induced LCN2 upregulation." (PMID 41436606, 2025). "Additionally, we observed a significant increase in IL‐1β and CD86 levels, indicating a shift towards a pro‐inflammatory tumour microenvironment that enhances immune‐mediated killing of cancer cells." (PMID 39193804, 2025). "Furthermore, IL-1β and CCL2 mutually enhance each other’s production, forming a feedback loop that amplifies macrophage infiltration into tumor tissues." (PMID 41341593, 2025). "Additionally, IL-1β reduces E-cadherin expression and increases MMP secretion, promoting tumor invasion." (PMID 40453286, 2025). "Conversely, M2 macrophages predominantly facilitate tumor progression by activating endothelial cell responses to growth factor signaling via CXCL12, IL-1β, IL-8, and Sema4d, thereby leading to the upregulation of angiogenesis-related genes and enhanced vascularization." (PMID 40563367, 2025). "The high level of IL-1β induced by NB-PTX might be due to debulking in the absence of ICOS-Fc, which can modulate IL-1β production in the tumor microenvironment." (PMID 41471045, 2025). "In addition, the expression levels of NLRP3, caspase-1, IL-1β, and NF-κB were markedly elevated in CRC, particularly in high-grade tumours." (PMID 41148809, 2025). "Functionally, SPP1+ TAMs play a central role in promoting tumor cell epithelial-mesenchymal transition (EMT), angiogenesis, intravasation, metastasis, and immunosuppression through the secretion of factors including SPP1, CCL18, CXCL8, TNF-α, and IL-1β." (PMID 41459510, 2025). "IL-6 and IL-1β can enhance CD274 expression in tumor cells by activating the JAK2/STAT3 signaling pathway, making it difficult to be recognized by T cells and facilitating tumor immune evasion." (PMID 39911394, 2025). "As commented on earlier, tumours actively secrete a variety of cytokines and pro-inflammatory mediators, including IL-6, TNF-α, and IL-1β, which can reach the adipose tissue and trigger the recruitment of immune cells, such as macrophages and T cells, leading to a chronic inflammatory state." (PMID 41373779, 2025). "The immune changes of RFA are generally less than that of cryoablation, for example, in colon cancer murine model, cryoablation augmented secretion of a wider array of cytokines including interleukin (IL)-1β, IL-5, IL-6, and IL-10 than RFA, with both anti-tumor and anti-inflammatory profiles." (PMID 40264767, 2025). "However, following anti-IL-1β treatment, SIRPa arose as the receptor on macrophages for VEGFs in the KPC-4545 tumor." (PMID 39948655, 2025). "However, inflammation-induced disruption of the BBB - mediated by TANs and cytokines (e.g. IL-1β, TNF-α, and IL-6) - can increase vascular permeability and create a permissive environment for tumor cell infiltration into the CNS." (PMID 40496607, 2025). "More specifically, this study found that the combination of anti-IL-1β and anti-PD-1 treatment does not slow primary tumor growth but reduces lung metastasis rate and prolongs overall survival in PDAC orthotopic murine model with lung metastasis tropism." (PMID 39948655, 2025).